TNF (tumor necrosis factor)
Diseases named in the same sentence as TNF in open-access papers (continued):
Sharing a sentence is not in itself a finding about the gene and the disease.
metabolic syndrome (continued). "We used TNFα as an inflammatory stimulus to mimic the dysfunctional endothelium, as it is a key cytokine in metabolic syndrome, and its circulating levels are elevated in metabolic syndrome patients." (PMID 31109070, 2019). "Horses with metabolic syndrome showed marked adipocyte hypertrophy and increased expression of adipokines (leptin) and inflammatory cytokines (TNFα,IL1β and CCL2) in both adipose tissue depots compared to healthy horses." (PMID 30866087, 2019). "Leukocyte adhesiveness was greater in the metabolic syndrome group than in the control group when samples of heparinized whole blood from metabolic syndrome patients and age-matched controls were perfused across TNFα-stimulated HUAEC." (PMID 31109070, 2019). "A randomised human study of patients with metabolic syndrome demonstrated a reduction in plasma concentrations of both IL-6 and TNF-α following 45 days of oral treatment with fermented milk containing Bifidobacterium lactis." (PMID 31618905, 2019). "Our data also showed that reperfusion injury following cerebral ischemia in metabolic syndrome rats increased TNF-α and IL-6 together with the cognitive impairment which were in agreement with the previous study." (PMID 30937145, 2019). "An energy-dense diet, which induces sequelae of the metabolic syndrome in humans and mice at least in part by enhancing pro-inflammatory TNFα formation, has recently been demonstrated to stimulate FGF23 production." (PMID 29807981, 2018). "Third, we didn’t measure the plasma hs-CRP, IL-6 and TNF in this study,then we cannot analyze these indexes’ effects on the development of dyslipidemia, we would take those indexes into account in further research." (PMID 30447693, 2018). "The positive associations between increasing IFN-γ or TNF-α and insulin, as well as TNF-α with cholesterol, in this study support a similar role of inflammation and elevated cytokines in metabolic syndrome in dolphins." (PMID 29304133, 2018). "The prolonged surge in pro-inflammatory cytokines such as tumor necrosis factor-alpha (TNF-α), interleukin (IL)-1, IL-6, and interferon-alpha (IFN-α) has been linked with dyslipidemia in studies following the chronic state of the HBV-infection." (PMID 29506525, 2018). "The main findings of the present study were a significantly lower level of the adiponectin/TNF-α ratio in GDM compared with normal pregnancy and significant associations of the ratio with metabolic syndrome biomarkers." (PMID 29387323, 2018). "Metabolic syndrome can transiently occur in lean individuals during infection, where increased secretion of TNF, IL-6 and IL-1 by macrophages induces a temporary insulin-resistant state." (PMID 29954107, 2018). "This indicated that in ADR induced the rat’s nephrotic syndrome, dyslipidemia leaded to the further damage of the kidney, and those changes were mediated through the elevated TNF-α and TGF-β1." (PMID 29569980, 2018). "Participants with metabolic syndrome who added three servings of dairy per day for six weeks found a reduction in TNF-α and MCP-1 when compared to a diet that contained energy matched control foods, but the decrease was only observed in women." (PMID 28817063, 2017). "On the other hand, metabolic syndrome can transiently occur in lean individuals during infection, where increased secretion of TNF, IL-6 and IL-1β by macrophages induces a temporary insulin-resistant state." (PMID 29295598, 2017). "They reported the efficacy of P. oleracea to increase the cell viability and improve dyslipidemia with different degrees, through antiinflammmtory effect, hence it lowers the levels of TNF- α and IL-6 that adipose cell secretes." (PMID 28077129, 2017). "Obesity and dyslipidemia induce abnormal growth of adipose tissue, contributing to the overproduction of inflammatory mediators [particularly TNF-α, IL-6, and interleukin-1 beta (IL-1β)] and activation of nuclear factor-kappa B (NF-κB)." (PMID 28725195, 2017).
metabolic syndrome (continued). "Age induced dyslipidemia is thought to be due to increased inflammation due to high levels of Tumor necrosis alpha (TNF- α) and interleukin-6 (IL-6) which interfere with lipid metabolism." (PMID 28761616, 2017). "Inflammatory mediators, including adipocyte-derived cytokines such as TNF-α, IL-6, and leptin, are known to induce dyslipidemia." (PMID 28947858, 2017). "Visceral adipose tissue is a component of the metabolic syndrome and is a major producer of IL-6, TNF-α, and MCP-1." (PMID 28642810, 2017). "Our group was the first to identify that ADAM28 is elevated in humans with the metabolic syndrome and is a novel sheddase of human tumour necrosis factor-α (TNF-α)." (PMID 28265178, 2017). "In metabolic syndrome patients, SFA consumption (38 E%) was associated with upregulation of pro-inflammatory genes (MMP-9 and TNF-α) and downregulation of anti-inflammatory genes (IκBα) in a postprandial state, compared with MUFA (43 E%), in PBMCs." (PMID 28076613, 2017). "Dyslipidemia (abnormal cholesterol levels in blood) and inflammation of the white adipose tissue, two lipid disorders in metabolic syndrome, have been correlated to inflammatory biomarkers such as cytokines TNF-α and IL-6 and the C-reactive protein." (PMID 27635405, 2016). "Although no one had previously reported hyperlipidemia being related to CU, it has been shown that there is an increased level of inflammatory markers such as IL-1, Il-6, and TNF-α in patients with CU and those with metabolic syndrome." (PMID 26964045, 2016). "TNF-α regulates the expression of NOS and thereby influences the production of NO, which is associated with prediabetic metabolic syndrome." (PMID 27619170, 2016). "In order to explore the possible mechanism of L-arabinose on metabolic syndrome, six target genes related to metabolism including TNF-α, leptin, IL-6, ACCα, CPT-1α, and CPT-1α were measured by real-time PCR in liver and adipose tissues." (PMID 26652604, 2015). "Metabolic syndrome is widely considered as a low-grade inflammatory state including inflammatory cytokine (TNF-α) and the chemokines (leptin and adiponectin)." (PMID 26652604, 2015). "We have previously shown elevated aortic ROS, nuclear factor kappa B activation and serum TNFα in animal models of metabolic syndrome that were significantly correlated with impaired NO production and endothelial dependent relaxation." (PMID 25889404, 2015). "miR-155 is induced by Toll-like receptor (TLR) ligands and it enhances the translation of tumor necrosis factor alpha (TNFα), a pro-inflammatory cytokine identified in the pathogenesis of the metabolic syndrome and steatohepatitis." (PMID 26042593, 2015). "At the white adipose tissue level, TNF-α has been shown to be over-expressed and was considered to be a linker between inflammation and metabolic syndrome." (PMID 26652604, 2015). "Inflammatory mediators such as TNFα are known to inhibit adipokine secretion and consequently contribute towards metabolic syndrome." (PMID 25714093, 2015). "The elevation of ALP, TNF-α, serum glucose and dyslipidemia lead us to suspect that HFD is able to induce aortic calcification for the WT." (PMID 26625143, 2015). "For example, TNFα attenuates the release of adiponectin from adipocytes which further complicates the pathology of metabolic syndrome." (PMID 25714093, 2015). "miR-155, a master regulator of inflammation, is induced by TLR ligands and enhances the translation of TNFα; a pro-inflammatory cytokine identified in the pathogenesis of metabolic syndrome and steatohepatitis." (PMID 26042593, 2015). "Investigations have shown that treatment with resveratrol, a potent antioxidant reduced dyslipidemia and TNF-α in visceral adipose tissue of obese Zucker rats." (PMID 26413386, 2015). "Blood pressure, body weight, body fat, triglycerides, insulin, HOMA-index, albuminuria, and TNF-α were increased in ovariectomized metabolic syndrome rats (p < 0.001)." (PMID 26491436, 2015).
metabolic syndrome (continued). "In fact, inhibition of COX results in decreased production of the pro-inflammatory cytokines, TNF-α, IL-6 and IL-1ß in LPS-stimulated macrophages and aspirin administration reduces plasma IL-1ß and IL-6 in patients with metabolic syndrome." (PMID 25638171, 2015). "A few studies have indicated relationships between elevated levels of inflammatory mediators, such as IL-6, TNF-α, and C-reactive protein levels, and metabolic syndrome." (PMID 25587268, 2014). "Our results showed that apoE-/- mice receiving vehicle alone developed severe atherosclerotic lesions and dyslipidemia, with significantly up-regulated levels of IL-6, TNF-α, VCAM-1 and MCP-1." (PMID 24621517, 2014). "Most of the recent studies showed that there was a correlation between inflammatory mediators (IL-6, TNF-α) and components of metabolic syndrome (MS)." (PMID 23865042, 2013). "A range of doses of aspirin (100 to 300 mg/day) reduced the plasma levels of inflammatory biomarkers such as CRP, IL-6 and TNF-α in patients with cardiovascular metabolic syndrome." (PMID 23506529, 2013). "As a proinflammatory cytokine, TNFα is responsible for the development of metabolic syndromes and the maintenance of metabolic homeostasis, exerting its actions through the immune and inflammatory pathways." (PMID 24324517, 2013). "As expected, this dolphin with metabolic syndrome and hyperinsulinemia displayed levels of TNF-α in the liver that were higher than the reference." (PMID 24101915, 2013). "Similar results were obtained in the research that up-regulation of pro-inflammatory cytokines like TNF-a, IL-6 and IL-12 were found in patients with dyslipidemia and in animal investigation of apoE−/− mice." (PMID 23472151, 2013). "The neutralization of TNF-α in obese rodent IS reported to improve the glycemic control and dyslipidemia." (PMID 22891067, 2012). "Before starting treatment with TNF-α blockers, consecutive PsA subjects with an active disease were evaluated for the presence of the metabolic syndrome (MetS), HS and CPs." (PMID 23036698, 2012). "Our results demonstrate that treatment with rosiglitazone alone is able to improve the hyperglycemia, dyslipidemia, and to decrease TNF-α, TGF-β, collagen-I and collagen-III and increased MMP-2 but within a minimal effect." (PMID 21450068, 2011). "The combined treatment is also able to improve dyslipidemia, and to decrease TNF-α, TGF-β, collagen-I and collagen-III and increased MMP-2 but within a greater effect than treatment with rosiglitazone alone." (PMID 21450068, 2011). "In obese Zucker rats, high doses of quercetin attenuates the metabolic syndrome and improves the inflammatory status in visceral adipose tissue evidenced by a reduction in TNF-alpha production, decreased fat iNOS expression, and an improved eNOS expression." (PMID 21876795, 2011). "An altered expression of ILs, TNFα, ICAM1 genes and of their respective receptors in adipose tissue as well as in PBMC has been implicated in the higher risk of suffering metabolic syndrome and cardiovascular disease." (PMID 20465828, 2010). "Plasma levels of TNF-α are altered in patients suffering from dyslipidemia and can be regulated by drugs interfering with lipid metabolic pathways." (PMID 21152327, 2010). "We can improve skin γδ T cells function in vivo by blocking TNFα, providing evidence that chronic TNFα in metabolic syndrome contributes to skin γδ T cell dysfunction in wound healing." (PMID 20625397, 2010). "Specifically, factors such as TNFα which are known to directly induce PPARβ/δ expression are increased in the chronic inflammation accompanying metabolic syndrome." (PMID 20300524, 2010). "Growing evidence suggests that TNF-α plays a directrole in metabolic syndrome, via direct effect of TNF-α on insulin signaling." (PMID 19148295, 2008).
metabolic syndrome (continued). "After 12–13 weeks on cafeteria diet, C57BL/6 mice had a phenotype of higher body weight, serum glucose and insulin, dyslipidemia, and had higher serum TNFα and similar IL-6 compared to normal diet controls." (PMID 18474108, 2008). "The metabolic syndrome is a pro-inflammatory state as evidenced by increased levels of IL-6, TNF-α, and C-reactive protein (CRP), serum amyloid A, and leptin and lower level of adiponectin." (PMID 17140429, 2006). "Brusatol dose-dependently suppresses proliferation and inflammatory mediator expression in TNF-α-induced HaCaT keratinocytes, ameliorates skin lesions and systemic dyslipidemia in mice, effectively normalizing serum TC and TG levels without inducing visceral organ toxicity." (PMID 41508030, 2026). "This dyslipidemia may be mediated by inflammatory cytokines (particularly TNF-α) through suppression of lipoprotein lipase (LPL) activity." (PMID 41508030, 2026). "Then, a reduction in IL-6 and IL-1β, but not in TNF-α, was observed after 8 weeks of consuming 75 g/day of whole grain products among overweight/obese individuals at risk of metabolic syndrome." (PMID 40944222, 2025). "Administration of honey from Heterotrigona itama bees (1 g/kg body weight) in metabolic syndrome-induced rats decreased brain pro-inflammatory tumour necrosis factor-alpha (TNF-α) and increased brain-derived neurotrophic factor essential for memory and learning." (PMID 39980683, 2025). "In this regard, an alteration of Raw, marked by an increase in pro-inflammatory parameters, such as leptin, IL-1 beta, IL-8, and TNF-alpha, and a decrease in anti-inflammatory parameters, such as adiponectin and IL-10, has been seen in older adults with metabolic syndrome." (PMID 40095561, 2025). "However, comparable levels of plasma TNF and IL-6 contradicted the expectation of low-grade inflammation in AO rats, at least judged by cytokine content, which is one of the hallmarks of metabolic syndrome." (PMID 40427746, 2025). "Moreover, supplementation with DHA extracts from the haptohyte Tisochrysis lutea in an animal model of metabolic syndrome lowered the plasma levels of the pro-inflammatory marker TNF-α, while increasing the production of the anti-inflammatory cytokine IL-10." (PMID 39997210, 2025). "Similarly, a significant increase in the mRNA expression levels of NF‐κB, IκBα, TNF‐α, IL‐1β, and IL‐6 was observed in the hypothalamus of metabolic syndrome mice." (PMID 40708775, 2025). "Most importantly, these data suggest that TNFα might play a larger role in the pathogenesis of metabolic syndrome that is initiated in this unique model." (PMID 40766326, 2025). "Many researchers consider interleukin-6 (IL-6) a marker of metabolic syndrome rather than a direct causal factor; however, during exercise, muscle fibers release IL-6 independently of tumor necrosis factor-α (TNF-α)." (PMID 41515940, 2025). "Additionally, in individuals with metabolic syndrome, 4 weeks of consuming anthocyanin-rich berries significantly down-regulated the expression of NF-κB-dependent genes, including TNF-α, IL-6, IL-1A, PCAM-1, and COX-2." (PMID 41156509, 2025). "Another study identified TNF-α as a major factor associated with decreased MMSE scores, suggesting that chronic inflammation contributes to neurodegeneration and impaired intellectual performance, particularly in individuals with metabolic syndrome." (PMID 40137151, 2025). "Accordingly, inhibition of TNF protects from metabolic syndromes, MASH and HCC development." (PMID 38874196, 2025). "Similar levels of plasma TNF and even lower levels of IL-6, when compared to DA rats, were previously noted in naïve female AO rats, which was in contrast to data obtained in obese/metabolic syndrome models in which higher IL-6 and TNF were detected in the blood of obese animals." (PMID 40427746, 2025).
metabolic syndrome (continued). "However, there is evidence in the literature that a single high-fat meal increases tumor necrosis factor α (TNF-α) concentration in patients with metabolic syndrome." (PMID 38674917, 2024). "We included age, gender (0=male, 1=female), Smoker (0=NO, 1=Yes), Drinker (0=NO, 1=Yes), thyroid-related hormones, IL-6, IL-15, TNF-α, dyslipidemia (0=NO, 1=Yes), and hypertension (0=NO, 1=Yes) as covariates to control for the influence of other relevant factors on LVM." (PMID 38356960, 2024). "In the MOD group, diabetic rats exhibited significantly elevated levels of TC, TG, HDL-C, and LDL-C in serum, along with increased levels of IL-6 and TNF-α in plasma, signifying the presence of dyslipidemia and a severe inflammatory response induced by the high-fat diet." (PMID 38708085, 2024). "In individuals with dyslipidemia, inflammatory factors such as interleukins and tumor necrosis factor-alpha are often elevated, which may promote the development of primary frozen shoulder through inflammatory pathways." (PMID 39882261, 2024). "TNF-α increases insulin resistance and promotes the release of fatty acids from the adipose tissue to the systemic circulation, thereby playing an important role in the pathogenesis of metabolic syndrome." (PMID 39771030, 2024). "This metabolic syndrome leads to local inflammation and an increase in systemic adipokine and pro-inflammatory cytokine levels, including adiponectin, leptin, tumor necrosis factor (TNF), IL-6, and CCL2." (PMID 39484071, 2024). "In a similar manner, chronic low‐grade inflammatory disorders and high level of TNF‐α in the metabolic syndrome may induce the development of brain IR." (PMID 39644152, 2024). "In another clinical trial, the interaction of the consumption of an olive-oil-enriched Mediterranean diet (compared with a low-fat diet) with two SNPs at the TNF-α gene promoter (rs1800629 and rs1799964) was described as a means to improve the markers related to metabolic syndrome." (PMID 39200288, 2024). "The purpose of the study was to investigate and differentiate the health-related factors associated with smokers’ TF and metabolic syndromes TF, and to analyze and differentiate the related epigenetic (COL-I and COL-II) genes and inflammatory (TNF-α) gene among all groups." (PMID 37853419, 2023). "In fact, it is well known that chronic inflammation states may induce dyslipidemia through the action of proinflammatory cytokines such as tumor necrosis factor- α or interleukin-6 perpetuating this visceral fat accumulation." (PMID 37764769, 2023). "Furthermore, a significant correlation was observed between femoral artery endothelial tissue damage and glycemia, AGEs, ET-1, TNF-α, and dyslipidemia." (PMID 36830898, 2023). "T2DM and metabolic syndrome are associated with a chronic state of low-grade inflammation, with increased serum levels of CRP and pro-inflammatory cytokines, such as IL-6, IL-1β and TNF-α." (PMID 38140319, 2023). "The results of the ROC analysis of indicators which are likely to be important in the diagnosis of the metabolic syndrome i.e. LAP or TNF-α, ranged between 0.8 and 0.7, which can be considered as a potential diagnostic value for clinical prognosis for patients." (PMID 36596839, 2023). "Furthermore, increased plasma levels of pro-inflammatory cytokines, such as TNF-α and IL-6, have been reported in people with severe IR, metabolic syndrome, T2D, and age-induced IR in elderly subjects." (PMID 37110230, 2023). "lactis HN019 intake in patients with metabolic syndrome led to reduced IL-6 and TNF-α levels." (PMID 37371961, 2023). "Among the components of metabolic syndrome, abdominal obesity is characterized by a chronic low-grade systemic inflammation, involving increased plasma pro-inflammatory cytokine levels such as interleukin-6 (IL-6) and tumor necrosis factor-alpha (TNF-α)." (PMID 35807489, 2022).